PROSER1 (proline and serine rich 1)
Description:
Mediates OGT interaction with and O-GlcNAcylation of TET2 to control TET2 stabilization at enhancers and CpG islands (CGIs).
Synonyms: C13orf23; bA50D16.2; FLJ12661
Tractability: PROTAC: ubiquitination databases record sites on it.
Gene: Protein-coding gene on chromosome 13 (39,009,865 to 39,038,096, reverse strand). Ensembl gene ENSG00000120685.
Subcellular location (Human Protein Atlas): Nucleoplasm; Cytosol
Gene Ontology:
Molecular function: protein binding
Genetic constraint (gnomAD): Loss-of-function variants: 14 observed, 36.62 expected, observed/expected ratio (o/e) 0.38, 90% interval 0.25 to 0.6. The upper end of that interval is the gene's LOEUF score, 0.6, which puts it in group 2 of 6, group 1 being the genes least tolerant of losing a copy. Missense variants: 840 observed, 916.84 expected, observed/expected ratio (o/e) 0.92, 90% interval 0.87 to 0.97. Synonymous variants: 401 observed, 387.06 expected, observed/expected ratio (o/e) 1.04, 90% interval 0.95 to 1.12.
Homologues: Orthologues: chimpanzee PROSER1 (99% identical), macaque PROSER1 (97% identical), rabbit PROSER1 (89% identical), guinea pig PROSER1 (89% identical), dog PROSER1 (88% identical), pig PROSER1 (83% identical), mouse Proser1 (79% identical), rat Proser1 (79% identical), tropical clawed frog proser1 (55% identical), zebrafish proser1 (41% identical).
Diseases named in the same sentence as PROSER1 in open-access papers:
PROSER1 is named in the same sentence as 8 diseases in open-access papers, as found by Europe PMC text mining. Sharing a sentence is not in itself a finding about the gene and the disease. The quoted sentences say what the papers report.
leukemia (1 paper, 2025). A malignant (clonal) hematologic disorder, involving hematopoietic stem cells and characterized by the presence of primitive or atypical myeloid or lymphoid cells in the bone marrow and the blood. "•Loss of PROSER1 impairs HSC function without compromising TET-mediated leukemia suppression." (PMID 40554416, 2025). "Here, we demonstrate that the leukemia-suppressive functions of TET2 are preserved in the absence of PROSER1." (PMID 40554416, 2025). "However, the precise role of PROSER1 in hematopoiesis and its relevance to TET-mediated leukemia suppression remains to be elucidated." (PMID 40554416, 2025).
myeloid leukemia (1 paper, 2025). A clonal proliferation of myeloid cells and their precursors in the bone marrow, peripheral blood, and spleen. "Although most mice that received transplant with TET2 KO cells succumbed to myeloid leukemia, with a median latency of 104 days, only 1 of 12 mice that received PROSER1 KO cells showed signs of distress and was observed to have transduced cells in the BM and spleen at the time of harvest." (PMID 40554416, 2025).
cancer (1 paper, 2022). A tumor composed of atypical neoplastic, often pleomorphic cells that invade other tissues. "Interestingly, loss of PROSER1 also recapitulates the DNA hypermethylation encroachment that occurs at H3K4me1-predisposed CGI borders in several cancers." (PMID 34667079, 2022).
cardiovascular diseases (1 paper, 2022). "In the dilated stage, TMEM205, ADIRF, C6H4orf48, NGRN, PROSER1, ERICH2, and CINP were not previously linked to cardiovascular diseases." (PMID 35625658, 2022).
hematological malignancies (1 paper, 2025). "We also noted that PROSER1 alterations, including missense, splice site, and frameshift mutations, have been identified in various hematological malignancies of both myeloid and lymphoid origin, albeit at much lower frequencies than TET2 mutations." (PMID 40554416, 2025). "Given the critical role of TET proteins in regulating hematopoietic differentiation and prevention of hematological malignancies, we hypothesized that PROSER1 deficiency may mimic the effects of TET2 mutations in hematopoiesis." (PMID 40554416, 2025). "Although PROSER1 deficiency does not appear to contribute to the development of TET-related hematological malignancies, it is likely to modulate DNA demethylation and potentially have additional functions in regulation of hematopoiesis." (PMID 40554416, 2025).
neurodevelopmental disorder (1 paper, 2025). A behavioral and cognitive disorder with onset during the developmental period that involves impaired or aberrant development of intellectual, motor, or social functions. "This interaction has been linked to neurodevelopmental disorders, as mutations in PROSER1 lead to developmental abnormalities, including craniofacial malformations, hypotonia, and sensorineural hearing loss in humans, mirroring defects observed in the knockout mouse model of PROSER1." (PMID 40001584, 2025).
tumor (1 paper, 2022). "Under normal conditions, PROSER1 might carry out a tumor-protective role by clearing DNA methylation from these CGIs through its regulation of TET1/2." (PMID 34667079, 2022).
PROSER1 also shares sentences with these, for which no sentence is quoted: esophageal squamous cell carcinoma (1 paper).